NOTCH2 (notch receptor 2)
Diseases named in the same sentence as NOTCH2 in open-access papers (continued):
Sharing a sentence is not in itself a finding about the gene and the disease.
ovarian carcinoma (15 papers, 2016 to 2026). A malignant neoplasm originating from the surface ovarian epithelium. "The high expression of Notch2 mRNA has been significantly associated with poor PFS for all ovarian cancer patients, especially in grade II ovarian cancer." (PMID 29104587, 2017). "Notch 2 mRNA high expression was associated with poor PFS in grade II ovarian cancer patients, HR 1.45 (1.07–1.96), p = 0.016." (PMID 28415574, 2017). "Genetic depletion or pharmacological inhibition of NOTCH2 with the γ-secretase inhibitor attenuated macrophage infiltration and sensitized tumor response to paclitaxel in multiple preclinical models of ovarian cancer." (PMID 41519773, 2026). "Currently, we have conducted whole-exome sequencing (WES) and targeted deep sequencing to validate new molecular markers, including NOTCH2, that impede the progression of cell malignancy in ovarian cancer (OC)." (PMID 37728427, 2023). "In a recent publication, it has been reported that high levels of NOTCH2 expression show a statistically significant correlation with poor overall and disease-free survival time and more advanced ovarian cancer stages." (PMID 35136410, 2022). "Ovarian cancer cells express Notch1, Notch2, Notch3, Notch4 and Jagged2, while ECs located in the ovary express Jagged1 and Dll1 and Dll4 ligands." (PMID 36430649, 2022). "Hes1 locus is amplified in 2–25% in breast and 2–22% in ovarian cancer, followed by Hey1, Notch2 and Notch3." (PMID 31470883, 2019). "Notch2 mRNA high expression was significantly correlated with poor PFS for all ovarian cancer patients, especially in grade II patients." (PMID 28415574, 2017). "Notch2 mRNA high expression was significantly correlated to poor PFS for all ovarian cancer patients, especially in grade II ovarian cancer patients." (PMID 28415574, 2017). "However, Notch2 mRNA high expression was significantly correlated to poor PFS for all ovarian cancer patients, HR 1.17 (1.02–1.33), p = 0.022." (PMID 28415574, 2017). "If the Notch2 missense mutations identified in these ovarian cancer TO cell lines renders the Notch2 protein nonfunctional, then a dysregulated Notch2 signaling pathway may be partially responsible for the observed carboplatin sensitivity." (PMID 34440225, 2021). "Thus Notch1 and Notch2 might be potential drug targets for some types of ovarian cancer patients." (PMID 28415574, 2017). "In this study, we found that Notch2 mRNA high expression was significantly correlated to poor PFS for all ovarian cancer patients, especially in grade II ovarian cancer patients." (PMID 28415574, 2017). "In addition, NOTCH2, NOTCH3, DLL3, MAML1, and ADAM17 were determined as the five most relevant genes in ovarian cancer." (PMID 35136410, 2022). "Notch2 mRNA high expression was not correlated to PPS in ovarian cancer patients, HR 1.09 (0.91–1.31), p = 0.34." (PMID 28415574, 2017). "Notch2 mRNA high expression was also not correlated to PPS in ovarian cancer patients, HR 1.09 (0.91–1.31), p = 0.34." (PMID 28415574, 2017). "Notch2 mRNA high expression was not correlated to OS for all ovarian cancer patients HR, 0.96 (0.84–1.1), p = 0.54." (PMID 28415574, 2017). "In addition, Notch2 mRNA high expression was not correlated to OS for all ovarian cancer patients HR, 0.96 (0.84–1.1), p = 0.54." (PMID 28415574, 2017).
B-cell lymphomas (14 papers, 2011 to 2025). "NOTCH2 plays an important role in marginal zone B cell development in the spleen and mutations in its pathway were identified in various B-cell lymphomas." (PMID 26498442, 2015). "Recently, some NOTCH2 mutations have been detected in some B-cell non-Hodgkin's lymphomas (B-NHLs) subtypes, such as DLBCLs and marginal zone lymphomas (MZLs), especially splenic marginal zone lymphomas (SMZLs, one subtype of MZLs)." (PMID 25314575, 2014). "There is a high structural similarity between NOTCH1 and NOTCH2 genes and recent NOTCH2 gain-of-function mutations are found in B-cell lymphomas." (PMID 23734977, 2013). "The gain-of-function mutations of NOTCH1 and NOTCH2 have been testified in B-cell lymphomas." (PMID 35204484, 2022). "This study provides new insights on novel downstream targets and pathways that are modulated by Notch2 in B-cell lymphoma." (PMID 33400727, 2020). "Based on RNA-Seq technology, the integrated global gene expression and signaling pathway activities in B-cell lymphoma were measured after knockdown of Notch2." (PMID 33400727, 2020). "The current study is the first of its kind, wherein comprehensive transcriptome analysis using RNA-Seq was performed in Notch2 depleted B-cell lymphoma cells." (PMID 33400727, 2020). "The volcano plot highlighted the significant DEGs that were modulated after knockdown of Notch2 in B-cell lymphoma (727 upregulated and 320 downregulated)." (PMID 33400727, 2020). "The truncate Notch2 activated both the Notch2 and the NF-κB signals and promoted the proliferation of B-cell lymphoma cell lines, including DLBCL and Burkitt's lymphoma cell lines." (PMID 25314575, 2014). "Activated Notch-2 also inhibited EBV entry into the lytic cycle in a B cell non-Hodgkin's lymphoma line by upregulating the cellular transcription factor Zeb2, which represses the transcription of BZLF1." (PMID 25122803, 2014). "In RAJI cells (Burkitt lymphoma) and SLVL cells (splenic B cell lymphoma), mutations of DNA-binding protein inhibitor ID-3 (ID3), transcription factor 3 (TCF3), and neurogenic locus notch homolog protein 2 (NOTCH2) increase phosphorylation of proteins in Akt/mTOR pathway." (PMID 33490663, 2021). "This minireview focuses on recent advances related to the mechanisms and roles of activated Notch1, Notch2, Notch3 and Notch4 signaling in human lymphocytic leukemia, myeloid leukemia and B cell lymphoma, as well as their significance, and recent advances in Notch-targeted therapies." (PMID 22128846, 2011). "However the role of Notch2 and the downstream pathways that it influences for development of B-cell lymphoma remains unclear." (PMID 33400727, 2020). "Similarly, NOTCH1 and NOTCH2 mutations are found in different B cell lymphomas, with NOTCH1 being recurrently mutated in chronic lymphocytic leukaemia (CLL) and NOTCH2 in marginal zone lymphoma." (PMID 31690218, 2019). "It has recently been reported that NOTCH2, activated via delta-like ligand 1, inhibits the EBV lytic cycle in the EBV-infected B-cell non-Hodgkin's lymphoma line by upregulating the cellular transcription factor Zeb2, which represses BZLF1 expression." (PMID 26018735, 2015). "However, the exact mechanism by which Notch2 regulates NF-kB activity via activating PI3K/AKT and inhibits apoptosis in B-cell lymphoma need to be determined." (PMID 33400727, 2020). "A wide range of Notch2 mutations have been identified with relevance to different cancers, but the role of Notch2 and its downstream pathways in development of B-cell lymphoma has not been comprehensively studied to date." (PMID 33400727, 2020). "However, more research is needed to determine whether or not NOTCH2 has any clinical significance in the prediction, diagnosis, or prognosis of B-cell lymphomas." (PMID 35204484, 2022).
prostate carcinoma (14 papers, 2011 to 2025). A carcinoma that arises from epithelial cells of the prostate gland. "Because of marginal effects and cell line-specific differences, we conclude that Notch2 activation has minimal impact on ability of SFN to induce apoptosis at least in prostate cancer cells." (PMID 22970326, 2012). "Collectively, these results indicated that SFN treatment resulted in cleavage of Notch1, Notch2, and Notch4 in both androgen-independent and androgen-responsive human prostate cancer cells." (PMID 22970326, 2012). "On the other hand, targeted depletion of Notch2 by siRNA as well as inhibition of Notch1 activation using DAPT augments prostate cancer cell motility inhibition by PEITC." (PMID 22039516, 2011). "We also demonstrate that activation of Notch1 and Notch2 reduces PEITC's ability to inhibit prostate cancer cell migration." (PMID 22039516, 2011). "In Doc-resistant prostate cancer cells, HES1 is upregulated as part of a broader activation of the Notch signaling pathway, which also involves increased NOTCH2 and Hedgehog signaling." (PMID 40507238, 2025). "Although most of the links between Notch receptors and prostate cancer involve NOTCH1, NOTCH2 was also found increased in several prostate cancer cell lines, with the highest levels expressed in the most aggressive ones, whereas NOTCH3/4 were not detectable." (PMID 35954292, 2022). "Among the MTA1-associated genes previously identified by our group from MTA1-ChIP analysis were Cyclin D1 and Notch 2, which were shown to be responsive to Pter treatment and directly regulated by MTA1 in prostate cancer cell lines." (PMID 33255879, 2020). "The present study used cultured human prostate cancer cells (PC-3, LNCaP, and LNCaP-C4-2B), and dorsolateral prostate tissues from control and SFN-treated TRAMP mice to determine the role of Notch1, Notch2, and Notch4 in anticancer effects of SFN." (PMID 22970326, 2012). "Similar to prostate cancer cells, PEITC treatment resulted in increased levels of cleaved Notch1 and Notch2 in PrEC cells especially at the 16-hour time point at both 2.5 and 5 μM concentrations." (PMID 22039516, 2011). "Exposure of human prostate cancer cells (LNCaP, PC-3, and DU145) and a normal human prostate epithelial cell line (PrEC) to PEITC resulted in cleavage (active form) of Notch1 and Notch2, and increased transcriptional activity of Notch." (PMID 22039516, 2011). "Consistent with literature data [28,] we also found that knockdown of Notch1 and Notch2 reduces migration of prostate cancer cells irrespective of the androgen-responsiveness." (PMID 22970326, 2012). "Specifically, knockdown of Notch1, Notch2 or Notch4 has no impact at all or only marginal effect on SFN-mediated inhibition of prostate cancer cell migration." (PMID 22970326, 2012). "PEITC-induced apoptosis in prostate cancer cells is modestly attenuated by knockdown of Notch2, but not by pharmacological inhibition of Notch1 activation." (PMID 22039516, 2011). "MiR-195-5p has been identified to interact with NOB1, NOTCH2 and CCNE1 in several cancers, while miR-195-5p has not been investigated in prostate cancer." (PMID 32440687, 2020).
type 2 diabetes (14 papers, 2008 to 2024). "The reported risk alleles of genetic variants rs10830963 in MTNR1B and rs10923931 in NOTCH2 were associated with diabetes mellitus type 2-related traits in GWA studies (P<5×10−8)." (PMID 28737528, 2017). "Higher fiber associated with lower type 2 diabetes risk only among risk allele carriers of the NOTCH2 variant and homozygotes of the risk allele of the ZBED3 variant." (PMID 27551309, 2016). "Higher fiber intake was observed to associate with lower incidence of type 2 diabetes only among risk allele carriers of the NOTCH2 variant and homozygotes for the risk allele of the ZBED3 variant." (PMID 27551309, 2016). "This SNP was 568kb to the transcription start site of NOTCH2, a gene associated with insulin release, insulin sensitivity, obesity and type 2 diabetes." (PMID 21738711, 2011). "Phylogenetic analysis demonstrates that rs2453058 is part of an ancient NOTCH2 gene variant (*1A01) which is associated with type 2 diabetes mellitus (T2DM) and is two times more frequent in Europeans than in East Asians, resembling the differences in CLL incidence." (PMID 39684291, 2024). "NOTCH2 was shown to be a susceptibility locus for type 2 diabetes mellitus." (PMID 28410202, 2017). "Furthermore, Notch2 SNPs have been reported in a number of GWAS studies associated with cardiovascular disease and type 2 diabetes." (PMID 28130354, 2017). "Given that insulin resistance may be a common underlying mechanism contributing to type 2 diabetes mellitus and hyperuricemia, the association of NOTCH2 with hyperuricemia might reflect the effect of this gene on type 2 diabetes." (PMID 28410202, 2017). "In addition, novel interactions between dietary fiber intake and two type 2 diabetes-associated variants in the NOTCH2 and ZBED3 loci were observed." (PMID 27551309, 2016). "This is a potential interpretation of results found for SNP rs10923931 (NOTCH2) in AA, where type 2 diabetes was the previously reported association for this SNP and the novel result was found for hypertension, and type 2 diabetes and hypertension are often a co-occurrence." (PMID 23382687, 2013). "The NOTCH2 locus was observed to interact with fiber intake on type 2 diabetes incidence (Pinteraction = 0.017)." (PMID 27551309, 2016). "A very recently published study investigated associations of the type 2 diabetes risk alleles in JAZF1, CDC123/CAMK1D, TSPAN8/LGR5, THADA, ADAMTS9, and NOTCH2 with obesity, insulin sensitivity, and insulin secretion in 4516 Danes." (PMID 18714373, 2008). "NOTCH2 is a common gene among AD, type 2 diabetes, and hypertension." (PMID 38790243, 2024). "The NOTCH2 risk allele did not associate with type 2 diabetes incidence in the whole population (HR 0.99; CI 0.91–1.09; P = 0.90); however, it was associated significantly with decreased risk of type 2 diabetes in the fourth fiber intake quintile (HR 0.75; CI 0.60–0.95; P = 0.015)." (PMID 27551309, 2016). "SNPs in TCF7L2, NOTCH2, and ZBED3 showed significant interactions with fiber intake on type 2 diabetes incidence (Pinteraction = 0.034, 0.005, 0.017, and 0.002, respectively)." (PMID 27551309, 2016). "Of the WNT-annotated SNPs (in genes upstream of TCF7L2), we found, in addition to TCF7L2, the SNPs in NOTCH2 and ZBED3 loci to significantly interact with fiber intake on type 2 diabetes incidence." (PMID 27551309, 2016). "In another study, allele-specific expression of several genes in islets (ANPEP, CAMK2B, HMG20A, KCNJ11, NOTCH2, SLC30A8 and WFS1) showed that even subtle changes of gene dosage may have significant consequences for development of type 2 diabetes." (PMID 30497374, 2018).
diabetes (12 papers, 2012 to 2024). "The observation that genetic variants in NOTCH2 interact with arsenic exposure to increase the risk of T2DM provides new insights into the pathogenesis of arsenic-related diabetes." (PMID 23967108, 2013). "Genetic variants of NOTCH2 reportedly can also increase susceptibility to diabetes mellitus." (PMID 30233306, 2018). "Dll4 with this extracellular domain induces disuse muscle atrophy and diabetes-induced muscle atrophy via Notch2." (PMID 38774645, 2024). "For example, instruments are from genes TCF7L2, IGF2BP2, NOTCH2, CDKAL1, PABPC4, FTO and JAZF1, known to be associated with diabetes and that have been further significantly associated with the metabolites." (PMID 39349772, 2024). "Novel variants in the genes ARAP1, GLIS3, MADD, NOTCH2 and WFS1 need further investigation to reveal their possible role in diabetes." (PMID 22662265, 2012). "A greater proportion of Notch2 positive cells was only noticed in distal tubular epithelial cells of diabetic rat groups compared to control groups at both investigated time points (p < 0.001), with a notably higher difference at two weeks after diabetes initiation." (PMID 36294921, 2022). "Further understanding the effects of these individual components, either alone or in combinations, on HG-stimulated EMT (or Notch2 activation) may provide helpful information to guide new licorice preparations for the treatment of renal tubulointerstitial fibrosis in diabetes." (PMID 31948095, 2020). "The NOTCH2 variant c.4228C>T/p.R1410C, found in P05, did not co-segregate with diabetes." (PMID 22662265, 2012). "Furthermore, this activation of Notch2 by ECs-derived Dll4 is essential for the progression of muscle atrophy seen in these pathologies, suggesting that this secreted Dll4 may be a potential therapeutic target for disuse muscle and diabetes-induced muscle atrophy." (PMID 38774645, 2024).
osteosarcoma (12 papers, 2009 to 2025). A usually aggressive malignant bone-forming mesenchymal neoplasm, predominantly affecting adolescents and young adults. "A study found that the expressions of NOTCH1, NOTCH2, Hes1, and Hey1 increased markedly in primary canine osteosarcoma." (PMID 36975516, 2023). "Immunoblot analysis revealed that over-expression of Notch 2 in osteosarcoma cell lines up-regulated protein levels of Notch intracellular domain (NICD) and Hes1, which are involved in Notch signaling." (PMID 31620362, 2019). "Notch 2 is an important receptor in Notch signaling and has been shown to regulate metastasis and tumorigenesis of osteosarcoma." (PMID 31620362, 2019). "Another study also found that HEY1 and other downstream target genes of Notch signaling including HES1, NOTCH1 and NOTCH2, were elevated in canine osteosarcoma by gene expression microarray analysis and reverse transcriptase - quantitative PCR (RT-qPCR)." (PMID 25023069, 2014). "Real-time PCR revealed that 10 of 10 human biopsy specimens of osteosarcoma increased Notch2 1.3–57.3-fold." (PMID 19455146, 2009). "This conflicts with a report that wt Dll4 cis-inhibited Notch2 in U2OS osteosarcoma cells." (PMID 39751380, 2025). "Furthermore, NOTCH2 signal activation can promote the proliferation of osteosarcoma cells by upregulating NICD2 and Hes1, while blocking NOTCH2 can inhibit the proliferation of osteosarcoma cells by restraining the progression of the G0/G1 phase of the cell cycle." (PMID 36975516, 2023). "Osteosarcoma tissues exhibit overexpression of SNHG12, which then leads to an increase in the tumorigenesis and metastasis induced by Notch2-and insulin-like growth factor 1 receptor (IGF1R) through the regulation of miR-195-5p." (PMID 38028627, 2023). "In this study, we found that Notch2, Jagged1, HEY1, and HEY2 were overexpressed in human osteosarcoma specimens." (PMID 19455146, 2009). "We found that Notch2, Jagged1, HEY1, and HEY2 were upregulated in the osteosarcoma biopsy specimens." (PMID 19455146, 2009). "A study found that the osteosarcoma LM-7 cell line, which showed highly invasive and metastatic features, markedly upregulated the expression of NOTCH1, NOTCH2, Dll1, and Hes1 compared with normal human osteoblasts and the Saos-2 cell line with low metastatic potential." (PMID 36975516, 2023). "Although, it was recently reported that DLL1, Notch1, Notch2, and HES1 are expressed in osteosarcoma cell lines, whether expression of Notch signalling molecules in osteosarcoma patient specimens is aberrant has not been clarified." (PMID 19455146, 2009). "We have previously shown that the osteosarcoma cell line K7M2 actively expresses Notch genes (Notch1, Notch2, and Notch4; Hes1), but not Notch3." (PMID 27378829, 2016). "However, the expression and clinical significance of NOTCH2 and NOTCH3 in osteosarcoma have not been reported." (PMID 36975516, 2023).